RHOA (ras homolog family member A)
Diseases named in the same sentence as RHOA in open-access papers (continued):
Sharing a sentence is not in itself a finding about the gene and the disease.
hepatocellular carcinoma (continued). "Overall, AFAP1-AS1 may promote NPC and hepatocellular carcinoma metastases through RhoA/Rac2 signaling." (PMID 29618386, 2018). "In addition, a long noncoding RNA was shown to indicate a poor prognosis of hepatocellular carcinoma via upregulation of RhoA/Rac2 signaling." (PMID 28029655, 2017). "Thus, the protein expression of DLC2 and RhoA were examined simultaneously in human hepatocellular carcinoma." (PMID 18651974, 2008). "As previous study indicated that DLC2 encodes a RhoGAP protein with growth suppressor function in hepatocellular carcinoma, we hypothesized that DLC2 may down-regulate expression of RhoA." (PMID 18651974, 2008). "Moreover, RhoA regulates expression of YAP mRNA in hepatocellular carcinoma cells." (PMID 41326667, 2025). "For example, SPON2 promotes the infiltration of M1‐like macrophages by affecting the activity of the RhoA‐Rho kinase signalling pathway, further inhibiting hepatocellular carcinoma (HCC) cells from invading adjacent tissues and migrating to distant sites." (PMID 31691494, 2020). "The lncRNA SchLAH (a seven-chromosome locus associated with hepatocellular carcinoma) is lowly expressed in HCC (hepatocellular carcinoma) and downregulates mRNA levels of RhoA and Rac1 in HCC cells." (PMID 31248165, 2019). "RhoA and Rac1 have been demonstrated to stabilize the HIF-1α protein, suggesting the possible cross-talk between small G-proteins and HIF pathways in hepatocellular carcinoma." (PMID 39941828, 2025). "In hepatocellular carcinoma, overexpression of GNAI1 significantly reduced metastatic capability by interfering with the RhoA-ROCK signaling pathway, a known regulator of cytoskeletal remodeling and cell motility." (PMID 40819057, 2025). "In malignant tumors, SAR1A exhibits complex roles, such as promoting osteosarcoma metastasis through the RhoA/YAP pathway and inhibiting ERK signaling, thereby suppressing the growth of hepatocellular carcinoma (HCC) cells." (PMID 39595043, 2024). "In hepatocellular carcinoma, RACGAP1 promotes cell proliferation and cytokinesis in coordination with Hippo pathway through increasing activity of RhoA and polymerization of filamentous actin." (PMID 38898473, 2024). "RACGAP1P, as a competitive endogenous RNA (ceRNA), is reported to be upregulated in hepatocellular carcinoma, resulting in the activation of the RACGAP1/RhoA/ERK pathway by the inhibition of miR-15-5p interference on RACGAP1 expression." (PMID 39858398, 2024). "The increased levels of RhoA‐GTP and ROCK in HUVECs were abolished by BMP9 overexpression in HBV‐infected hepatoma cells." (PMID 37132170, 2023). "Previously, it has also been found that COL4A2 activates the RhoA/ROCK pathway to facilitate the growth and metastasis of hepatocellular carcinoma (HCC) cells." (PMID 34477476, 2021). "In hepatocellular carcinoma cells, the increase of invasion induced by RND1 depletion is mediated by the activation of RHOA." (PMID 31344837, 2019). "FTY720 down-regulated the active form of RhoA in pancreatic cancer cells 53, reduced levels of active Rac in hepatocellular carcinoma 78,79 as well as decreasing levels of ROBO1 and ROCK1 (targets of RhoA) in glioblastoma cells." (PMID 26171944, 2015). "In line with these biochemical assays, we also demonstrated co-localization of peroxisomes and RhoA by transfecting myc-G14VRhoA, a dominant-active mutant of RhoA, into mouse AT3 hepatoma cells." (PMID 21079737, 2010). "Our results also revealed that Grp78 overexpression in SMMC7721 cells decreased RhoA-GTP level, and Grp78 siRNA knockdown rescued RhoA-GTP level in Grp78 overexpressing cells, indicating Grp78 inhibited RhoA activity in hepatocellular carcinoma cells." (PMID 20082722, 2010). "In hepatocellular carcinoma, GEF-H1 promotes cell motility via activation of RhoA signaling." (PMID 35681428, 2022).
hepatocellular carcinoma (continued). "Moreover, in hepatocellular carcinoma, it is indicated that RACGAP1 can activate RhoA to function, and it was verified that RACGAP1 enhances the stability of ECT2 to improve ECT2-mediated RhoA activation." (PMID 39858398, 2024). "However, the expression of DLC2 protein, and its relationship with RhoA in clinical hepatocellular carcinoma have not been studied." (PMID 18651974, 2008). "In hepatocellular carcinoma CTHRC1 promotes cell adhesion through activation of integrin β1 and phosphorylation of focal adhesion kinase (FAK), while the activation of RhoA, but not Rac1 or Cdc42 plays a crucial role." (PMID 27430622, 2016). "Researches show that DLC2 suppresses cell transformation by means of inhibition of RhoA activity in hepatocellular carcinoma cells, meanwhile DLC2 mRNA is underexpressed in human hepatocellular carcinoma, which suggested a potential prognostic value of DLC2 for HCC patients." (PMID 18651974, 2008). "Although DLC2 has been identified as a tumor suppressor gene in HCC, the expression of DLC2 protein, especially the relationship with RhoA in clinical hepatocellular carcinoma has not been studied." (PMID 18651974, 2008).
pancreatic cancer (64 papers, 2010 to 2025). "This is consistent with our previously published data showing a significant effect of cerivastatin, pitavastatin, and simvastatin on RHOA gene expression in pancreatic cancer cells cultured in vitro." (PMID 40722786, 2025). "Different mechanisms have been proposed as mediators of the effect of eIF5A in pancreatic cancer, including facilitating the translation of a specific subset of proteins such as RhoA and Ras." (PMID 38229033, 2024). "Circ-IRAS entered HUVECs via pancreatic-cancer-cell-derived exosomes and significantly downregulated miR-122 and ZO-1 levels and upregulated RhoA and RhoA-GTP levels, thereby increasing endothelial monolayer permeability and promoting tumor metastasis." (PMID 37046819, 2023). "In pancreatic cancer, HNRNPC induced DNA damage repair and cancer-associated fibroblast activation through the RhoA/ROCK2-YAP/TAZ signaling pathway." (PMID 37469973, 2023). "The generated products miR-1207-5p and miR-1207-3p inhibit sarcoma gene (SRC) and ras homolog family member A (RhoA), respectively, to increase the sensitivity of pancreatic cancer cells to gemcitabine chemotherapy." (PMID 35965522, 2022). "In pancreatic cancer cells, DESI2 overexpression leads to upregulation of Ras homolog gene family member A (RhoA) and Rho‐associated protein kinase, proteins which are known to be involved in stress fiber formation." (PMID 35943635, 2022). "Recently, RhoA/ROCK-mediated PI3K/Akt activation via csGRP78 has been shown in pancreatic cancer cells." (PMID 33799579, 2021). "’s report, NORAD promotes the tumor cell migratory and invasive abilities in pancreatic cancer through modulation on the hsa-miR-125a-3p-metiated RhoA axis." (PMID 34551785, 2021). "For example, eIF5A regulates pancreatic cancer metastasis by modulating expression of RhoA and ROCK53." (PMID 33547280, 2021). "For instance, lncRNA NORAD promotes pancreatic cancer metastasis through enhancing epithelial–mesenchymal transition via targeting hsa-miR-125a-3p to increase RhoA expression." (PMID 34307380, 2021). "NORAD increases epithelial–mesenchymal transformation and promotes pancreatic cancer metastasis via the NORAD/hsa-miR-125a-3p/RhoA axis." (PMID 32267831, 2020). "ASICs sense the extracellular acidification (common in pancreatic cancer) and in response, increase intracellular Ca2+ levels and activate RhoA signaling." (PMID 32629766, 2020). "By the use of a FRET biosensor for RhoA, Timpson and colleagues showed that RhoA activation at the invading front of the pancreatic cancer is critical for the invading capacity of pancreatic cancer." (PMID 32270554, 2020). "Tamoxifen inhibits the myofibroblastic differentiation of pancreatic stellate cells (PSCs) in the tumor microenvironment of pancreatic cancer in an acto‐myosin‐dependent manner via RhoA‐mediated contractility, YAP deactivation, and GPER signaling." (PMID 30538117, 2019). "Meanwhile, downregulating [Ca2+]i with calcium chelating agent BAPTA-AM or knockdown of RhoA with siRNA also significantly repressed acidity-induced EMT of pancreatic cancer cells." (PMID 28518134, 2017). "We found that RhoA knockdown significantly repressed acidity-induced migration and invasion of pancreatic cancer cells, supporting a role of RhoA in acidity-induced EMT." (PMID 28518134, 2017). "To choose the best cell line for the study, we first assessed the expression of Cdc42, RhoA and Rac1 in a panel of pancreatic cancer cell lines." (PMID 28410221, 2017). "Collectively, our study highlights a mechanism for acidity-induced EMT in pancreatic cancer cells through ASIC1/3-[Ca2+]i-RhoA axis, which contributed to the metastasis of pancreatic cancer." (PMID 28518134, 2017). "We also found that the depletion of ARHGEF15 by RNA interference in pancreatic cancer cell lines downregulated the activities of molecules of the Rho signaling pathway, including RhoA, Cdc42 and Rac1." (PMID 27145964, 2016).
pancreatic cancer (continued). "We showed that upregulation of ARHGEF15 in pancreatic cancer increased activation of the Rho-family proteins, especially RhoA, Cdc42 and Rac, resulting in enhanced motility of the pancreatic cancer cells." (PMID 27145964, 2016). "Atorvastatin was also shown to influence the cellular activities of components of the PI3/AKT signaling molecules such as AKT, P2X7, pERK, RhoA, cyclin D1, and β-catenin to inhibit proliferation and induce apoptosis in pancreatic cancer cells." (PMID 26229958, 2015). "Our study is the first to show that Notch regulates the phosphorylation of PTEN through the RhoA pathway in pancreas cancer." (PMID 22074495, 2011). "Taken together, these findings suggest that P61-E7 is a promising GGTI compound and that RhoA is an important target of P61-E7 in Panc-1 pancreatic cancer cells." (PMID 22028818, 2011). "Taken together, our findings show that P61-E7 provides a novel addition to the range of GGTI compounds that are in development as anticancer drugs and that RhoA is an important target of the GGTI compound in Panc-1 pancreatic cancer cells." (PMID 22028818, 2011). "We also examined the mechanism of action of P61-E7 in this paper, and our work suggests that RhoA is a major player in GGTI-mediated effects on pancreatic cancer cells." (PMID 22028818, 2011). "Moreover, DCLK1 silencing by microRNA-195 can downregulate RhoA expression in pancreatic cancer cells, indicating that DCLK1 also has an interaction with RhoA." (PMID 36369000, 2022). "Furthermore, LINC00857 regulates the miR-130b/RHOA axis, which in turn enhances the malignant characteristics of pancreatic cancer." (PMID 36359832, 2022). "Moreover, lncRNA NORAD enhances pancreatic cancer metastasis through promoting epithelial–mesenchymal transition via targeting hsa-miR-125a-3p to increase RhoA expression." (PMID 34307380, 2021). "Because the RhoA signaling cascade is activated in pancreatic cancer, inhibitors of the RhoA signaling cascade may provide a promising molecular target for anticancer drugs." (PMID 32270554, 2020). "Interestingly, RhoA inhibition by p190A or its C-terminus domain was suggested as a new approach in pancreatic cancer treatment." (PMID 31013840, 2019). "Additionally, we show that both compounds preferentially down-regulate Rac1 activity compared to Cdc42 and RhoA in pancreatic cancer cells." (PMID 28410221, 2017). "Mechanistically, NORAD may function as a ceRNA to regulate the expression of RhoA through competition for miR-125a-3p, thus playing an oncogenic role in the pathogenesis of pancreatic cancer." (PMID 29121972, 2017). "iv) the TGF-beta signalling pathway which is most significantly involved in EMT induction in pancreatic cancer cells through activation of ERK/MAPK, PI3K, p38, JNK, RhoA, and other signalling pathways." (PMID 36591282, 2022). "As NORAD is relatively new in the field, only one study has shown its ceRNA potential through its competition for miR-125a-3p with RHOA (ras homolog family member A), to promote EMT and metastasis in pancreatic cancer." (PMID 29702599, 2018). "In MiaPaCa-2 cells, RHOA and RALA signaling pathways were found essential for KRAS dependent regulation of migration and invasion required for pancreatic cancer metastasis." (PMID 27835861, 2017). "Inhibition of ASIC1 and ASIC3 with siRNA or pharmacological inhibitor significantly decreased [Ca2+]i and its downstream RhoA during acidity and, thus, suppressed acidity-induced epithelial–mesenchymal transition (EMT) of pancreatic cancer cells." (PMID 28518134, 2017).
pancreatic cancer (continued). "We found that hypoxia can increase NORAD expression and stimulate EMT in pancreatic cancer cells and that NORAD promotes EMT and metastasis by regulating RhoA in a miR-125a-3p-dependent manner." (PMID 29121972, 2017). "CTHRC1 promoted tumor cell migration and invasion by activating Wnt/PCP signaling supported by activating Rac1 in pancreatic cancer, activating RhoA in HCC and activating both Rac1 and RhoA in GIST cells." (PMID 29285247, 2017). "The most important new finding in this study is that ASIC1 and ASIC3 transduce the acidic pH to elevation of [Ca2+]i concentration and RhoA activity, promoting EMT of pancreatic cancer cells during acidic microenvironment." (PMID 28518134, 2017). "We found RhoA is the most important small GTPase for CTHRC1-mediated HCC invasion and they found Rac1 accounts for the invasiveness in pancreatic cancer." (PMID 23922981, 2013). "Taken together, these data strongly suggest that EGF induces the activation of ROCK via RhoA, and that the phosphorylation of cofilin and MLC by EGF occurs through ROCK in Panc1 pancreatic cancer cells." (PMID 21722395, 2011). "Our results provide evidence that both RhoA and RhoC are the targets of BITC in pancreatic cancer cells." (PMID 22016776, 2011). "Previous studies have demonstrated that Arhgap25 regulates the proliferation of human pancreatic cancer cells via HIF-1α, leading us to hypothesize that RhoA modulates glycolytic processes through Arhgap25/HIF-1α pathway." (PMID 40846818, 2025). "ASIC1 and ASIC3 are mainly expressed on the membrane of pancreatic cancer cells and upregulated in pancreatic cancer tissues, and ASIC1 and ASIC3 promote acid-induced EMT of pancreatic cancer by activating the Ca2+/RhoA pathway, leading to the metastasis of pancreatic cancer." (PMID 38505262, 2024). "In summary, we found that exosomes derived from pancreatic cancer cells were taken up by HUVECs and that circ-IARS carried by these exosomes specifically absorbed miR-122 in HUVECs to inhibit its expression and relieve its inhibition of the target gene RhoA." (PMID 30064461, 2018). "Together, these results indicate that RhoA is involved in the EMT of pancreatic cancer cells induced by ASIC1/3-[Ca2+]i activation in acidic microenvironment, highlighting that RhoA is a major effector of acidity-induced EMT of pancreatic cancer." (PMID 28518134, 2017). "Furthermore, knockdown of RhoA with RNAi significantly inhibited the acidity-induced EMT and weakened the invasion and migration of pancreatic cancer cells." (PMID 28518134, 2017). "In addition to the elevated expression of RhoA, increased levels of ROCK have been reported to be observed in esophageal squamous cell carcinoma, bladder cancer and pancreatic cancer." (PMID 21722395, 2011).
glioma (62 papers, 2008 to 2025). A benign or malignant brain and spinal cord tumor that arises from glial cells (astrocytes, oligodendrocytes, ependymal cells). "Our analysis implicated multiple Atrx target genes in glioma cell motility, including Gna13, whose direct transcriptional upregulation and downstream signaling through RhoA GTPases promoted mNPC migration." (PMID 29535300, 2018). "For instance, Gal-1-induced migration of glioma cells has been associated with modifications to actin cytoskeleton organization and the increase in small GTPase RhoA expression." (PMID 27459991, 2016). "CD44/CD155-silencing significantly inhibited the invasive phenotype of glioma cells associated with decreased expression of some of the key mediators of invasion, particularly F-actin, integrins, Rac 1/2/3, RhoA and Cdc42." (PMID 22363471, 2012). "Our study showed that ITGB8-TGFβ1 affected downstream activation of Smad2/3 and RhoA in glioma cells." (PMID 35676251, 2022). "NGFR-expressing glioma cells in humans enhance migration, induce structural rearrangement of the actin cytoskeleton, and reduce RhoA activity, which are closely related to cell invasion." (PMID 35954323, 2022). "In a study done on glioma cells, cell motility decreased following the overactivation of RhoA using oligodendrocyte lineage transcription factor 2 (OLIG2)." (PMID 32089990, 2020). "A study done on glioma cells provides further evidence that transmembrane metalloproteinase (MT1-MMP) is regulated by RhoA through the ROCK signaling pathway." (PMID 32089990, 2020). "In this context, the RhoA/ROCK signaling pathway is upregulated in glioma cells, promoting cell migration and proliferation." (PMID 33240883, 2020). "Although there are several possible mechanisms for TRPC6-mediated regulation of the RhoA/Rock pathway in glioma progression, this still needs to be confirmed in the context of this neoplastic disease." (PMID 33240883, 2020). "Drp1 knockdown also reduces the formation of actin protrusions and invasiveness of glioma cells by regulating the RHOA/ROCK pathway, known to regulate cytoskeletal dynamics." (PMID 32184231, 2020). "RhoA activity can promote the activation of FAK, suggesting an additional mechanism for TRPC6-RhoA mediated tumoral progress in glioma." (PMID 33240883, 2020). "Third, we also found that NKCC1 regulated EMT through the Rac1 and RhoA signaling pathways in gliomas." (PMID 30159893, 2019). "Inhibition of the RhoA target ROCK led to increased migration in glioma cells via an activation of Rac1 and Rac1 inhibition was associated with reduced migration and invasion." (PMID 31003495, 2019). "The mutual inhibition of RhoA and Rac1 is further complicated by Cdc42 being capable of activating Rac1 in glioma." (PMID 31003495, 2019). "As for the associations of RhoA and ROCK1 with other miRNAs, another study has demonstrated that ROCK1 protein expression was greatly inhibited by miR-145 in the human glioma cell lines, which is in line with our study." (PMID 31541994, 2019). "This study demonstrates that the prevalent activation of AKT in gliomas increases the ER protein-folding capacity and enables tumor cells to utilize a side effect of RhoA activation: the perturbation of the IRE1α-mediated decay of SPARC mRNA." (PMID 31062076, 2019). "For example, responses in glioma invasion with suppression of myosin II and/or activation of Rac and RhoA are significantly variable depending on physical microenvironments." (PMID 31075964, 2019). "The same is true for glioma cells, showing an increased expression of the mutually inhibiting GTPases RhoA and Rac1." (PMID 31003495, 2019). "Specific inhibition or knockdown of NKCC1 both attenuate activated Rac1 and RhoA, and the pharmacological inhibitions of Rac1 and RhoA both impair the invasion and migration abilities of gliomas." (PMID 30159893, 2019).